CGAS (cyclic GMP-AMP synthase)
Diseases named in the same sentence as CGAS in open-access papers (continued):
Sharing a sentence is not in itself a finding about the gene and the disease.
tumor (continued). "Professor Li’s research shows that hyperbaric oxygen (HPO) can promote the teniposide-induced activation of the cGAS-STING signaling pathway, enhancing the anti-tumor efficacy of PD-1 antibodies in HCC." (PMID 40098962, 2025). "Increased cytosolic DNA activates the cyclic GMP-AMP synthase stimulator of interferon genes (cGAS-STING) protein pathway, further propagating a pro-inflammatory tumoricidal response in tumor-draining lymph nodes and regional lymphatics." (PMID 41357581, 2025). "To confirm that BRQ activates the cGAS-STING signaling pathway in vivo, we analyzed tumor tissues to assess p-STING and IFN-β expression levels." (PMID 41144149, 2025). "It is also known that activation of the cGAS-STING pathway and simultaneous suppression of PD-L1 immunosuppressive factors effectively overcomes tumor resistance to radiotherapy and immunotherapy." (PMID 41007722, 2025). "The cGAS-STING pathway is a crucial component of innate immunity, playing a dual role in tumor biology by promoting pro-inflammatory responses and anti-tumor immunity." (PMID 40831989, 2025). "Upon internalization into TAMs via the NVs, plant-derived mtDNA induced cGAS-STING, promoting the conversion of anti-tumor macrophages." (PMID 40075527, 2025). "RFWD3 inhibited cGAS‐STING signaling by stabilizing TREX1 and degrading dsDNA, leading to the accumulation of MDSCs and suppression of anti‐tumor immunity." (PMID 41117130, 2025). "The cGAS-STING pathway, in particular in dendritic cells, has emerged as a critical intrinsic tumour-detecting mechanism." (PMID 40368781, 2025). "This transfer enhances the immunosuppressive activity of PMN-MDSCs via the cGAS–STING–NF-κB signaling pathway, thereby promoting tumor progression." (PMID 41282600, 2025). "Despite cGAS-STING cascade activation, programmed death-ligand 1 (PD-L1) downstream was also upregulated in tumor cells following DMPtNPS and radiotherapy combination." (PMID 39885557, 2025). "ICD is characterised by calreticulin exposure, HMGB1 release, and activation of the cGAS-STING pathway, which together prime anti-tumour immunity." (PMID 41226343, 2025). "Mechanistically, this disruption leads to persistent DNA damage, activating the cGAS-STING pathway in both HCC cells and M1 macrophages, which drives PD-L1 expression via STING-IRF3-STAT1 signaling, promoting immunosuppression and tumor progression." (PMID 40546347, 2025). "In GC, the knockdown of PRMT1 suppresses the cGAS/STING pathway, leading to the generation of type I interferon and facilitating M1‐like macrophage polarization within the tumor microenvironment." (PMID 41256732, 2025). "Radiated tumor cell-derived microparticles (RMPs) are radiotherapy mimetics that have been shown to activate the cGAS-STING pathway, induce tumor cell ferroptosis, and inhibit M2 macrophage polarization." (PMID 38705987, 2024). "The dsDNA released into the cytoplasm is recognised by cyclic GMP-AMP synthase (cGAS), thereby activating the stimulator of interferon genes (STING) pathway in both tumour cells and DCs." (PMID 38816831, 2024). "During non‐apoptotic cell death, we have recognised how miMOMP, downstream activation of cGAS, STING‐IFN and other pathways, inducing sustained DNA damage, affects tumour cell biological changes." (PMID 39030903, 2024). "It activates the cGAS‐IFN‐I pathway, leading to an increase in CD8+ central memory (TCM)‐like cells and improves CD8+ T cell‐mediated anti‐tumor immunity." (PMID 38900071, 2024). "Conversely, cGAS–STING-dependent activation of NC-NF-κB signaling can drive IL6/STAT3 signaling and EMT programs, which promote tumor growth and metastasis, respectively." (PMID 39295867, 2024). "Herein, it is reported that various tumor‐derived exosomes carry ENPP1, and can hydrolyze synthetic 2′3′‐cGAMP and endogenous 2′3′‐cGAMP produced by cells to inhibit cGAS‐STING pathway in immune cells." (PMID 38498770, 2024).
tumor (continued). "While the cGAS/STING pathway shows promise as a complementary therapeutic target in cancer treatment, it plays a dual role in both tumour elimination and tumorigenesis." (PMID 39403376, 2024). "(c) The combination of Mn2+ and PTX synergistically triggers the activation of the cGAS–STING pathway, which promotes antigen presentation, and the activation of tumor-specific CD8+ T cells." (PMID 38715912, 2024). "Tumour cell death was accompanied by the release of IFN-β, TNF-α, and IL-6 (attributed to cGAS/STING activation in the surrounding immune milieu following immunogenic cell death), all of which are drivers of anti-tumour inflammation." (PMID 39403376, 2024). "Recent research revealed that PRMT1 can inhibit the enzymatic activity of cGAS in part through PRMT1-mediated Arg methylation, thereby suppressing the anti-tumor immune response of cells." (PMID 40018367, 2024). "Taken together, these interactions demonstrate the complex interplay between cGAS-STING signaling and the tumor microenvironment, as well as the significance of these factors when considering pharmacologic interventions." (PMID 38659582, 2024). "Studies have shown that the downstream product of the cGAS-STING pathway, IL-6, can activate the STAT3 signaling pathway in tumors, thereby promoting tumor growth." (PMID 38523155, 2024). "Through the cGAS-STING pathway, DAMPs, such as calreticulin, ATP, and HMGB1, promote DCs and macrophages’ recognition of tumor antigens and facilitate the infiltration of CD8+T cells into tumors, thereby stimulating tumor immunity." (PMID 38853203, 2024). "The interaction between tumor cells and other cell types via the interleukin‐4 (IL4)/IL4 receptor (IL4R) pair was considerably enriched in cGAS+/STING+ Tfh tumor cells." (PMID 38145335, 2024). "Du and colleagues discovered that a significant enrichment of the Clostridia class can enhance antigen presentation and effector T cell function through the cGAS-STING-IFN-I pathway, thereby boosting anti-tumor immune responses." (PMID 38911378, 2024). "As a cytoplasmic PRR and a DNA sensor, cGAS activates the IFN pathway by recognizing cytoplasmic DNA, including DNA released from viruses, bacteria, mitochondria, tumor cells, or dead cells." (PMID 38807595, 2024). "Differences and heterogeneity in the expression of cGAS and p‐STING were found by the detection of a tissue chip using IF assay composed of 70 DLBCL tumour tissues and 15 normal lymph nodes." (PMID 39183480, 2024). "Further, it was found by immunohistochemical detection that the expression of cGAS protein and the level of STING phosphorylation in tumor tissues were remarkable decreased compared with those in adjacent tissues." (PMID 39054486, 2024). "LNM has effectively demonstrated the ability to activate the cGAS-STING signaling pathway, induce the production of pro-inflammatory cytokines, and inhibit tumor development." (PMID 38675217, 2024). "RECQL4 repairs dsDNA released by tumor cells during RT, suppresses cGAS‐STING signaling in DCs, and prevents radiation‐induced tumor immune awakening." (PMID 38381090, 2024). "A complicated picture is emerging from recent investigations of the cGAS/STING DNA sensing pathway in the context of cancer progression and anti-tumor immunity." (PMID 39043779, 2024). "T-DXd induces the DDR, activates an immune response through the cGAS-STING pathway, and enhances DC activation and PBMC-mediated tumor cell killing." (PMID 39449023, 2024). "The existence of these metal ions in the tumor maintains the RT-induced cGAS-STING activation and enlarges the RT-triggered anti-tumor immunity." (PMID 38831378, 2024). "Significant correlations were observed between the transcript levels of MB21D1 (cGAS), TMEM173 (STING), and KDM6A (UTX) in the scRNA‐seq data of mice tumor infiltrating NK cells." (PMID 39206412, 2024).
tumor (continued). "We further determined the cGAS-STING pathway-related protein expression and cytokine secretion in tumor tissue through western blotting assay and ELISA." (PMID 39613774, 2024). "Taken together, these results suggest that H101 infection activates cGAS transcription by increasing the level of H3K4me3 at the cGAS promoter in SW620 and LOVO tumor cells." (PMID 38782895, 2024). "The diverse roles of the cGAS-STING pathway as an innate immune signaling pathway in detecting intracellular imbalances and initiating strong anti-tumor immune responses have garnered considerable attention." (PMID 39420203, 2024). "In the hypoxic milieu, the PTT/PDT attributes of the nanoprobe are also remarkably boosted, inducing strong tumor-specific T-cell immune responses and mitigating immunological resistance through the synergistic activation of both ICD and cGAS-STING pathways." (PMID 39613774, 2024). "Subsequently, cGAS stimulates the activation of the cGAS-STING pathway by sensing the accumulation of dsDNA, thereby enhancing anti-tumor immunity." (PMID 38566036, 2024). "The enrichment levels of cGAS, cGAS+/STING+, and CSPS were higher in Tfh tumor cells than in non‐Tfh cells and the RR group than in the ND group." (PMID 38145335, 2024). "Activation of cGAS-STING pathway promotes the transcription of type I IFNs and has previously been reported to promote anti-tumor immunity in many preclinical models 31-33." (PMID 38993569, 2024). "Tumor‐intrinsic IFN activation is mainly dependent on two factors: dsRNA fragments recognized by RIGI‐MAVS signaling and dsDNA fragments recognized by cGAS‐STING signaling." (PMID 39031630, 2024). "Since PRMT1 inhibits the cGAS-STING signaling pathway in tumors, methods to directly or indirectly restore cGAS activity and levels can enhance the anti-tumor immune response of cancer cells." (PMID 40018367, 2024). "In tumor‐draining lymph nodes, there was a decrease in CD8+ T cells in cGAS−/− mice, along with reduced CD8+ and CD4+ TCM‐like cells, increased naive cells, and a significant decrease in Tfh cells." (PMID 38900071, 2024). "It has been shown previously that CIN can activate chronic cGAS-STING signaling, which can promote tumor metastasis and survival through TBK1-independent activation of NC-NF-κB and IL-6-STAT3 signaling." (PMID 38167338, 2024). "DCs exhibit a unique characteristic in their cGAS-STING pathway activation, specifically their active uptake of tumor-derived DNA." (PMID 38523155, 2024). "Although tumor cells themselves often fail to elicit a type I IFN response after radiation, dsDNA released from dying tumor cells is sufficient to activate cGAS-mediated type I IFN pathways in DCs." (PMID 38256021, 2024). "Using various genetically engineered mouse models, we found that tumor‐derived RECQL4 inhibited cGAS‐STING pathway activation in dendritic cells and anti‐tumor immune reorganization after RT, thereby reducing the sensitivity to HCC treatment." (PMID 38381090, 2024). "DNA damage induced by radiotherapy and the accumulation of cytoplasmic DSBs also activate the cGAS–STING pathway and its downstream NF‐κB pathway, leading to the production of SASP and enhanced anti‐tumour effect." (PMID 39270064, 2024). "In recent years, the role of the cGAS-STING pathway in cancer, particularly within the tumor microenvironment, has garnered significant attention." (PMID 39439455, 2024). "Our studies provide a framework for novel HDTs that target the cGAS-STING pathway to promote M.tb containment and anti-tumor immunity." (PMID 38095464, 2024). "In the TME, activation of the cGAS-STING pathway mediates the activity of immune cells, including the maturation of DCs, cross-priming of tumor-related antigens, and cytotoxic T-lymphocytes." (PMID 38999073, 2024). "The activation of cyclic GMP‐AMP (cGAMP) synthase (cGAS) and its adaptor, stimulator of interferon genes (STING), is known to reprogram the immunosuppressive tumor microenvironment for promoting antitumor immunity." (PMID 38898748, 2024).
tumor (continued). "The activation of the cGAS-STING pathway has been shown to enhance immune responses and inhibit carcinogenesis in various tumor models, suggesting its anti-tumor potential." (PMID 38238314, 2024). "Mechanistically, PS activated the cGAS‐IFN‐I pathway, leading to an increase in CD8+ TCM‐like cells and improved CD8+ T cell‐mediated anti‐tumor immunity." (PMID 38900071, 2024). "cGAS-STING signaling has been reported to play an important role in microbial infection, chronic inflammation, tumor progression, and organ degeneration." (PMID 38643466, 2024). "Our analysis indicated that both cGAS and STING were expressed at higher levels in tumor vs. adjacent normal tissues, thereby confirming the activation of the cGAS-STING pathway." (PMID 39050705, 2024). "This is in line with the observation that NK cell cytotoxicity against tumor cells requires STING expression by host cells and cGAS expression by cancer cells." (PMID 39544936, 2024). "likened IFN-I to the bridge between the cGAS-STING pathway and CD8+ T cell-mediated anti-tumor immunity." (PMID 39464890, 2024). "Succinic acid produced from F. ucleanum suppresses the anti-tumor response by preventing CD8+ T lymphocytes from entering the tumor microenvironment (TME) in vivo and blocking the cGAS interferon-β pathway." (PMID 39567970, 2024). "This was coupled with efficient activation of the cGAS/STING pathway, through phenanthridine-induced DNA damage, resulting in type 1 interferon release and the genesis of an anti-tumour immune profile in the TME." (PMID 39403376, 2024). "Lactobacillus rhamnosus (LGG) further enhances anti-tumor immune responses, especially CD8+ T-cell activity, by activating the cGAS-STING pathway and inducing IFN-β release from dendritic cells (DCs)." (PMID 39867908, 2024). "In recent investigations, emerging research has elucidated the intricate connection between the cGAS-STING pathway and tumor immunity." (PMID 38240703, 2024). "cGAS-STING pathway has been recognized as a promising target for improving immune response and suppressing tumor progression." (PMID 38592428, 2024). "Intriguingly, we also detected activation of the cGAS-STING signaling pathway in CAR-Ms and SIRPα-silenced CAR-Ms upon coculture with tumor cells." (PMID 39379603, 2024). "Previous studies have shown that cGAS-STING can promote metastasis and tumor progression in certain contexts, likely through chronic inflammation and recruitment of myeloid-derived suppressor cells." (PMID 39449023, 2024). "Activation of cGAS-STING signaling pathway can induce apoptosis in tumor cells and promote activation of immune cells, thereby suppressing tumor growth and metastasis." (PMID 39295867, 2024). "Next, we attempted to reactivate silenced cGAS by using the oncolytic adenovirus H101 in SW620 and LOVO tumor cells." (PMID 38782895, 2024). "The cGAS‐STING pathway is a cytosolic DNA sensing pathway of particular interest, since in recent years it has been shown to play a major role in tumor control." (PMID 38193112, 2024). "This highlights the important role of tumor‐derived exosomes in the innate immune response and deepens our understanding of the ENPP1‐mediated cGAS‐STING pathway." (PMID 38498770, 2024). "T-DXd promoted cGAS-STING pathway activation through TOP1cc, leading to IFN-I production, DC activation, and enhanced CD8+ T cell-mediated tumor killing." (PMID 39449023, 2024). "Imbalanced cGAS‐STING signalling has been found to have involvement in malignant diseases and exhibited dual roles in tumours." (PMID 39183480, 2024). "To quantify MOMP activity in tumour samples, we established specific pathways reflecting MOMP activity, including apoptosis, pyroptosis, cGAS/STING, inflammasome and NF‐kB pathways, through previous literature mining and summarising." (PMID 38899748, 2024).
tumor (continued). "The downstream interferons (IFNs) mediated by cGAS-STING can not only activate innate immunity but also prompt T-cell priming and tumor infiltration." (PMID 38332843, 2024). "By activating cGAS‐STING in TAMs, the immunosuppressive TME was converted with the increased level of proinflammatory cytokines and chemokines, as well as enhanced tumor infiltration of cytotoxic T cells." (PMID 38898748, 2024). "In vitro, both pharmacological inhibition and genetic targeting of VPS34 enhance cGAS-STING-mediated expression and secretion of CCL5 and CXCL10 across various tumor cell types." (PMID 40395527, 2024). "Lastly, the release of tumour antigens, in conjunction with cGAS/STING activation, potentiated dendritic cell maturation and activation, thus facilitating the recruitment and activation of anti-tumour immune cells." (PMID 39403376, 2024). "Emerging evidence has confirmed that m6A methylation affects the activation of innate immune pathways such as TLR, cGAS-STING, and NLR by regulating RNA metabolism, revealing its potential mechanisms in the innate immune response of tumor cells." (PMID 39403369, 2024). "To further exclude the role of tumor-intrinsic STING under tumor-intrinsic cGAS overexpression background, we knocked out Sting in Cgas overexpression cells and found that Sting deficiency (Cgas (+)/Sting (−)) did not alter tumor growth compared to parental cells (Cgas (+)/Sting (+))." (PMID 38177099, 2024). "Furthermore, the fact that cGAS or STING-deficient MMRd cell lines grow faster than the cGAS or STING-proficient MMRd counterparts in immunocompetent mice supports the idea that anti-tumor immunity does not solely rely on the expression of neoantigens." (PMID 39544936, 2024). "Cyclic GMP-AMP (cGAMP) synthase (cGAS) /stimulator of interferon genes (STING) pathway acts as intermediaries between IR-triggered DNA damage and interferon I-induced CD8+ T cell anti-tumor effects, mounting cytotoxity of IR and immunotherapy against tumors." (PMID 38977778, 2024). "The presence of mitotic DNA in the cytoplasm can trigger activation of the cGAS-STING pathway, a critical innate immune response within the tumour microenvironment." (PMID 38796460, 2024). "As we expected, decreased tumor growth and prolong mice survival phenotype disappeared both in OGT rescued cells and in OGT/cGAS or OGT/STING double knockout tumors." (PMID 38168435, 2024). "After activation of the cGAS-STING pathways, type I interferon production is instrumental in DC maturation and its cross-presentation of tumor antigens (TAs) to antigen-specific CD8+ T cells, which exerts adaptive antitumor immunity." (PMID 38185685, 2024). "For tumor immunotherapy to be successful, stimulating the Cyclic-GMP-AMP synthase (cGAS) signaling pathway and establishing a proinflammatory immune environment are essential." (PMID 39290276, 2024). "Collectively, these findings indicate that tumor cGAS and host STING mediates vascular normalization and anti-tumor immune response in an interdependence manner." (PMID 38177099, 2024). "The results elucidate the essential function of tumor exosomal ENPP1 in the cGAS‐STING pathway, furthering understanding of the crosstalk between the tumor cells and immune system." (PMID 38498770, 2024). "Both IFN-I and cGAS-STING agonists induce cellular apoptosis, but IFNs primarily affect tumor cells, whereas STING agonists impact various immune cell types, including T and B cells." (PMID 38512518, 2024). "Macrophages take up this group of hypoxia-derived exosomes and miR-25/93, inhibiting the cGAS-STING pathway, reducing IFN-β secretion, and downregulating M1 polarization-related gene expression (CXCL9 and CXCL10), thereby reducing anti-tumor immunity." (PMID 39464890, 2024). "The expression patterns of cGAS-STING pathway members in GBM tissue samples were compared in relation to primary and recurrent tumours, and to PTEN genotypes of the patients." (PMID 38214828, 2024).